GPNMB (glycoprotein nmb)
Diseases named in the same sentence as GPNMB in open-access papers (continued):
Sharing a sentence is not in itself a finding about the gene and the disease.
melanoma (continued). "GPNMB is expressed in tumors across cancer types, such as breast cancer, melanoma, hepatocellular carcinoma, prostate cancer, osteosarcoma, and lung cancer, where it plays an important role in regulating cancer cell migration, invasion, metastasis, and treatment resistance." (PMID 40626360, 2025). "Nevertheless, GPNMB+ cells appear to be crucial for melanoma dissemination." (PMID 40528051, 2025). "GPNMB encodes the transmembrane protein glycoprotein nonmetastatic melanoma protein B and co-immunoprecipitated with α-syn in cells to influence disease progression." (PMID 39483867, 2024). "Glycoprotein NMB (GPNMB, a DC-associated transmembrane protein; also known as DC-HIL/osteoactivin) is an endogenous type 1 transmembrane glycoprotein that was initially shown to be highly expressed in melanoma cell lines with low metastatic capacity." (PMID 38351314, 2024). "Glycoprotein NMB (GPNMB) expression has been described in melanoma, glioma and breast cancer." (PMID 38730739, 2024). "Likewise, GPNMB can enhance the proliferation and spread of melanoma and propel tumor advancement by means of an immunosuppressive mechanism that hinders T cell activation." (PMID 38706915, 2024). "GPNMB is a melanocyte-expressed gene with expression dependent on MITF transcription, and the latter was associated with the tricarboxylic acid cycle to regulate the hypoxic response in melanoma." (PMID 38552245, 2024). "One of these molecules is GPNMB whose role in enhancing immunosuppression has been increasingly confirmed in malignancy, such as melanoma, breast cancer, glioma, and gastric cancer, which may offer an attractive target for cancer immunotherapy." (PMID 38140790, 2023). "In melanoma, 87% of tumors demonstrate membrane expression of gpNMB." (PMID 35159045, 2022). "In BRAF mutant melanomas, GPNMB is upregulated after BRAF/MEK inhibitor therapy." (PMID 35158847, 2022). "The consistency between our results and Jeff’s indicates that the canine melanoma genes described here (in particular, GPNMB) may potentially be useful biomarkers targets in both canines and humans." (PMID 34570764, 2021). "Primary melanoma and the surrounding tissue clearly stained with GPNMB (left)." (PMID 33564068, 2021). "High expression of GPNMB promotes tumor migration and invasion by interacting with integrins to localize immune-suppressive and pro-angiogenic cells to the tumor and renders melanoma resistant to BRAF and MEK inhibitors." (PMID 34570764, 2021). "Mutations in GPNMB are reported in COSMIC but it is not clear if they are causative events in melanoma." (PMID 34570764, 2021). "GPNMB is related to mutations in BRAF and MEK that do cause melanoma." (PMID 34570764, 2021). "We began our study by verifying and validating the specificity of anti-GPNMB antibody in our own experimental systems using melanoma cells, as well as normal human epidermal melanocytes (NHEMs), a cell type in which GPNMB expression has been well characterized, as positive controls." (PMID 32188902, 2020). "However, different studies have indicated that GPNMB is highly expressed in dendritic cells, hepatocellular carcinoma, gliomas, squamous cell lung carcinoma, melanoma, soft tissue tumors, and cancer of the breast, stomach, and pancreas." (PMID 30400781, 2018). "Moreover, the lack in our lists of melanosome markers, such as DCT and GPNMB, excluded any possible contamination with melanosomes, known to be abundantly secreted from melanoma cells." (PMID 30290833, 2018). "GPNMB is highly expressed in high-grade glioma, and its specific scFv antibodies and immunotoxins present feasibility as reagents in the immunotherapy of malignant gliomas and melanomas." (PMID 30484490, 2018). "In addition, expression of GPNMB is well documented in melanoma cells as well as other types of cancer cells." (PMID 30586924, 2018).
melanoma (continued). "By employing GPNMB-specific scFv antibodies or immunotoxins, there was significant anti-tumor activity observed in GPNMB-expressing glioma and malignant melanoma cells in vitro as well as malignant glioma xenografts in mouse and melanoma neoplastic meningitis in vivo model." (PMID 30484490, 2018). "Our results might also be relevant in another context: GPNMB is expressed at higher levels in melanoma and breast cancer." (PMID 25889792, 2015). "Interestingly, imatinib, as described here for primary moDC, induced GPNMB expression in melanoma and glioblastoma cell lines." (PMID 25889792, 2015). "Furthermore, GPNMB has been reported to be overexpressed in several cancers, including melanoma, breast, and gastric cancer 14–16." (PMID 26077887, 2015). "Previously works have showed that GPNMB is expressed in all stages of melanomas or melanocytes." (PMID 22912767, 2012). "GPNMB is highly expressed in several tumor types such as melanoma, glioblastoma and breast cancer." (PMID 21209915, 2010). "GPNMB is preferentially expressed in low-metastatic melanoma cell lines as glycoprotein." (PMID 19750230, 2009). "However, GPNMB, expressed in melanoma cell lines, was preferentially expressed in low-metastatic cell lines (OMIM: *604368)." (PMID 16026605, 2005). "Furthermore, GPNMB is a potential cancer target, with high expression in most melanoma metastases." (PMID 39875968, 2025). "Moreover, GPNMB was upregulated in metastatic QQ cells, as compared to their primary counterparts, and, among the “growth inhibitory genes” of the melanoma-metastasis gene MODULE_488, it emerged as the most significantly upregulated gene specifically in metastatic quiescent cells." (PMID 40528051, 2025). "Cells that co-stained with CD68 and GPNMB were scattered in the compound nevi, whereas in the in situ and vertical melanomas and lymph-metastasized melanoma, these co-stained cells were located internal to the melanoma cells or within the tumor microenvironment (B and EV1A)." (PMID 38719996, 2024). "Administration of an anti‐GPNMB monoclonal Ab (mAb) or completely GPNMB knockout on CD11b+Gr1+ cells, could abrogate CD11b+Gr1+ cells expansion, impact their suppressor function on T cells, and diminish melanoma development in vivo." (PMID 38140790, 2023). "Notably, such gene encodes the glycoprotein non-metastatic melanoma protein B (GPNMB), a molecule that plays a role in motility processes, such as invasion and metastasis, in poorly metastatic melanoma cells." (PMID 37006485, 2023). "Knockdown of GPNMB could reduce melanoma growth in immunocompetent mice." (PMID 34108545, 2021). "Other significantly reduced proteins include TRAIL, TGFR-2, ANXA1, SPARC, FURIN, GPNMB, and ERBB2, all of which play roles in melanoma progression, immune modulation, or resistance to targeted therapies." (PMID 40725203, 2025). "To validate that these cells were indeed melanophages, we immunostained three independent patient specimens with a melanoma marker HMB45, the mature melanosome marker GPNMB, and a pan-macrophage marker CD68." (PMID 38719996, 2024). "The elevated expression of GPNMB and VCAM-1 has beenobserved inmany cancers including breast cancer, melanoma, and prostate cancers.Such overexpression of GPNMB and VCAM-1 has been associated with poorprognosis and increased cancer metastasis." (PMID 37067377, 2023). "Accordingly, glembatumumab vedotin, a gpNMB-targeted MMAE-conjugated ADC, resulted in a 39% ORR in a phase I/II study conducted among patients with advanced melanoma refractory to ICI and BRAF/MEK inhibition, with acceptable toxicity (NCT00412828)." (PMID 35159045, 2022). "By contrast, in normal cells, gpNMB is restricted to intracellular compartments, therefore suggesting gpNMB as a promising ADC target in melanoma." (PMID 35159045, 2022). "An antibody anti-GPNMB (called CDX-011 or glembatumumab vedotin) has been evaluated in phase I/II trials as a treatment for advanced breast cancer and melanoma." (PMID 34054862, 2021).
melanoma (continued). "In SK-MEL-28 melanomas, which contain only stage I and II melanosomes, and WM266-4 melanomas, which contain only stage I melanosomes, GPNMB is expressed normally." (PMID 22912767, 2012). "Suda and colleagues successfully revealed Glycoprotein nonmetastatic melanoma protein B (GPNMB), which was initially found in melanoma cell lines, as a transmembrane protein that is highly expressed in senescent endothelial cells." (PMID 39578455, 2024). "Glycoprotein non-metastatic melanoma B (GPNMB)/osteoactivin was first identified in the human melanoma cell lines." (PMID 39263169, 2024). "Glycoprotein non-metastatic melanoma protein B (GPNMB) is a transmembrane protein enriched on the surface of some cells, including melanoma, glioblastoma, and macrophages." (PMID 37112900, 2023). "In addition, GPNMB adheres to PAM212 keratinized cells in an RGD-dependent manner and is possibly involved in melanocyte development, melanin synthesis, and melanoma production." (PMID 37627399, 2023). "Glycoprotein non-metastatic melanoma protein B (GPNMB) is a transmembrane glycoprotein originally identified in human melanoma cells." (PMID 37941897, 2023). "GPNMB was identified as a key gene regulating the involvement of alveolar type II epithelial cells in EMT and was originally identified as a type I transmembrane glycoprotein in a hypermetastatic melanoma cell line." (PMID 37468937, 2023). "In line with the observation that gpNMB expression is induced by the inhibition of MAPK pathway, combination of glembatumumab vedotin with MAPK pathway inhibitors demonstrated a synergistic therapeutic effect in a melanoma mouse model." (PMID 35159045, 2022). "These genes along with their activation values Eq for melanoma (MEL) are, GPNMB (MEL activation = 18.59), UBL3 (MEL activation = 1.39), AP1S2 (MEL activation = 1.28), RAB38 (MEL activation = 0.91), EDNRB (MEL activation = 0.55), JUN (MEL activation = 0.34), and C1orf21 (MEL activation = -0.13)." (PMID 34570764, 2021). "GPNMB with expression value of 18.59 is significantly expressed for melanoma in this study and is characteristic of Jeffs non-migratory sub-group 2 human cell lines showing up regulation of this gene." (PMID 34570764, 2021). "Similarly, GPNMB inhibitors have been explored for various types of cancer, for instance the monoclonoal antibody glembatumab (CDX-011) in Phase 2 trials for melanoma and breast cancer." (PMID 33417599, 2021). "Glycoprotein non-metastatic melanoma protein B (GPNMB) is a transmembrane glycoprotein named for being highly expressed in a melanoma cell line along with low metastatic properties." (PMID 29519253, 2018). "Glycoprotein non-metastatic b (GPNMB), a highly expressed protein in melanoma and breast cancer, plays an important role with modulation, and is an important target in ADC." (PMID 29329556, 2018). "GPNMB was discovered in melanoma cells as glycoprotein nonmetastatic melanoma B (GPNMB) and is also known as osteoactivin and dendritic cell-associated heparin sulfate proteoglycan-dependent integrin ligand." (PMID 29799853, 2018). "Glycoprotein nonmetastatic B (GPNMB) is a potential oncogene that is particularly expressed in melanoma and breast cancer (BC)." (PMID 26077887, 2015). "GPNMB, a type-I transmembrane glycoprotein, shows expression in the lowly metastatic human melanoma cell lines but does not show expression in the highly metastatic cell lines." (PMID 19750230, 2009). "GPNMB is a type I transmembrane protein that was originally identified in melanoma cell lines and is preferentially expressed by non-metastatic cell lines, suggesting that it may inhibit tumorigenesis." (PMID 35444208, 2022). "CDX-011, or Glembatumumab (Celldex), is an antibody targeted against GPNMB (Transmembrane Protein NMB); this antibody was conjugated to vedotin (monomethyl auristatin E), a highly potent antimitotic agent, in recent Phase 2 trials for advanced breast cancer and late-stage melanoma." (PMID 22566752, 2012).
melanoma (continued). "Furthermore, studies including knockout of GPNMB in vitro or xenograft assays are needed to assess the biological role of GPNMB, although prior studies have demonstrated GPNMB-targeting ADC could inhibit growth of tumor and induce complete regression in melanoma xenografts." (PMID 34108545, 2021). "CXCL9, CXCL10, PD-L1, CD86, IL-10, TREM2, GPNMB, IL-4l1 and FOLR2 markers showed widespread expression by most melanoma TAMs, with no definition of a particular macrophage subset, and regardless of whether the tumor was metastasizing or not." (PMID 40406129, 2025).
breast cancer (61 papers, 2007 to 2025). A primary or metastatic malignant neoplasm involving the breast. "Follow-up Mendelian randomization analyses provided weak evidence for a causal role of 2 of these proteins in type 2 diabetes-related cancer, specifically furin and glycoprotein Nmb in breast cancer risk." (PMID 38290287, 2024). "Specifically, increased GPNMB expression has been linked to poorer prognosis in breast cancer patients, and mutations in the GPNMB gene have been named as causal of the skin pigmentation disorder amyloidosis cutis dyschromica (ACD)." (PMID 38368938, 2024). "Substantial evidence indicates that GPNMB is implicated in disease progression in glioblastoma, melanoma and breast cancer." (PMID 34583655, 2021). "When endogenously produced by tumor cells from breast cancer and cholangiocarcinoma, GPNMB expression was associated with the ability to form spheroids in vitro containing elements with CSC properties." (PMID 34583655, 2021). "gpNMB was associated with worse outcome in breast cancer patients, particularly those with a triple negative phenotype." (PMID 28108739, 2017). "To address whether the GPNMB/OA-associated angiogenic phenotype was specific to the 66cl4 mouse mammary tumor model, we next interrogated the association between GPNMB/OA expression and vascular density in human breast cancer cells and primary tumors." (PMID 20711474, 2010). "This common mechanism functions in prostate cancer invasion, breast cancer bone metastasis, and lung cancer metastasis, serving as the core pathway through which GPNMB promotes cross-cancer metastasis." (PMID 41180454, 2025). "GPNMB emerges as a key oncogenic driver in breast cancer, particularly in aggressive subtypes, through multifaceted mechanisms." (PMID 41180454, 2025). "It is intriguing that CHI3L1 was proposed to promote ovarian cancer malignancy by enhancing tumor stemness, while GPNMB exerted an analogous function in breast cancer." (PMID 40204276, 2025). "NRP1 expression is increased by glycoprotein NMB (GPNMB), and NRP1 and GPNMB cooperate to stimulate mammary tumor growth." (PMID 37894289, 2023). "To further validate the spatial distribution of Mreg macrophages in metastases, we performed immunofluorescence imaging of EO771 breast cancer lung metastases, using GPNMB as a marker for the Mreg population." (PMID 37756565, 2023). "It is known that GPNMB plays a crucial role in different kinds of diseases, such as various cancers like glioma, breast cancer, hepatocellular carcinoma, and gastric cancer, chronic obstructive pulmonary disease, obesity, and so on." (PMID 37786733, 2022). "When GPNMB-positive cells form spheres in breast cancer, the expression levels of CSC markers such as SOX2, NANOG, OCT4, CD44, CD133, and FOXO3 are elevated." (PMID 36061142, 2022). "The mechanism of tumor recurrence and the exact role of GPNMB in breast cancer is still under discussion." (PMID 34108545, 2021). "To investigate the clinical significance of GPNMB in primary breast cancer, we quantified GPNMB expression of each specimen using IHC." (PMID 34108545, 2021). "Breast cancer cells expressed high level of cell surface-GPNMB showed elevated cancer stem cells genes and EMT transcriptional factors genes exhibiting high tumorigenicity." (PMID 34108545, 2021). "We found that basal and claudin-low subtypes had GPNMB overexpression in contrast to other breast cancer subtypes based on gene expression classifier PAM50." (PMID 34108545, 2021). "In breast cancer, a common gynecological malignancy, overexpressed GPNMB plays roles as mediator in metastasis to bone as well as in aggressively lung-metastatic breast cancer." (PMID 30484490, 2018). "GPNMB expression has also been reported in breast cancer in more than 60% of tumors in stroma and in 10% in tumor epithelium." (PMID 29799853, 2018). "In gynecological cancers, GPNMB also plays an important role in the progression of breast tumors and the metastasis of breast cancer." (PMID 30484490, 2018).